PPM1M (protein phosphatase, Mg2+/Mn2+ dependent 1M)
Synonyms: PP2C-eta; PP2CE; PP2Ceta; FLJ32332
Tractability: PROTAC: its protein half-life has been measured.
Gene: Protein-coding gene on chromosome 3 (52,245,741 to 52,250,616, forward strand). Ensembl gene ENSG00000164088.
Subcellular location: Nucleus
Subcellular location (Human Protein Atlas): Nuclear bodies
Gene Ontology:
Molecular function: manganese ion binding; protein serine/threonine phosphatase activity
Biological process: protein dephosphorylation
Cellular component: nucleus
Genetic constraint (gnomAD): Loss-of-function variants: 41 observed, 47.92 expected, observed/expected ratio (o/e) 0.86, 90% interval 0.67 to 1.11. The upper end of that interval is the gene's LOEUF score, 1.11, which puts it in group 4 of 6, group 1 being the genes least tolerant of losing a copy. Missense variants: 527 observed, 541.27 expected, observed/expected ratio (o/e) 0.97, 90% interval 0.91 to 1.05. Synonymous variants: 212 observed, 215.76 expected, observed/expected ratio (o/e) 0.98, 90% interval 0.88 to 1.1.
Homologues: Orthologues: chimpanzee PPM1M (99% identical), macaque PPM1M (98% identical), rabbit PPM1M (92% identical), pig PPM1M (91% identical), mouse Ppm1m (89% identical), rat Ppm1m (83% identical), guinea pig PPM1M (78% identical), dog PPM1M (77% identical), zebrafish ppm1h (45% identical), zebrafish ppm1j (43% identical), Caenorhabditis elegans ppm-1.H (39% identical), Drosophila melanogaster CG17598 (37% identical), and 12 more. Paralogues in human: PPM1H (46% identical), PPM1J (44% identical), PDP2 (20% identical), PPM1F (20% identical), PPM1E (20% identical), PDP1 (19% identical), PPM1N (19% identical), ILKAP (18% identical), PPM1L (17% identical), PP2D1 (17% identical), PPM1A (17% identical), PPM1K (17% identical), and 4 more.
Diseases named in the same sentence as PPM1M in open-access papers:
PPM1M is named in the same sentence as 35 diseases in open-access papers, as found by Europe PMC text mining. Sharing a sentence is not in itself a finding about the gene and the disease. The quoted sentences say what the papers report.
Parkinson disease (2 papers, 2025). A progressive degenerative disorder of the central nervous system characterized by loss of dopamine producing neurons in the substantia nigra and the presence of Lewy bodies in the substantia nigra and locus coeruleus. "We also identified a rare PPM1M mutation in patients with Parkinson’s disease that is catalytically inactive when tested in vitro and in cells." (PMID 40690364, 2025). "We have also identified a rare PPM1M mutation in patients with Parkinson’s disease that is catalytically inactive when tested in vitro and in cells." (PMID 40166354, 2025).
autoimmune thyroid disease (1 paper, 2023). Inflammatory disease of the thyroid gland due to autoimmune responses leading to lymphocytic infiltration of the gland. "The results showed that high PPM1M expression was highly correlated with immune-related pathways, including cell adhesion molecules, cytokine receptor interactions, and autoimmune thyroid disease." (PMID 36961170, 2023).
bipolar disorder (1 paper, 2024). A disorder of the brain that causes unusual shifts in mood, energy, activity levels and the ability to carry out day-to-day tasks. "It is plausible that PPM1M could be a key driver of the effect of these drugs: it is the top PhenomeXcan gene for bipolar disorder; a recent study found loci in this gene to be associated with schizophrenia; and another study linked the locus to rare mental illness." (PMID 38736684, 2024).
bladder cancer (1 paper, 2023). "In this study, immunohistochemistry was used to examine the expression levels of PPM1M in bladder cancer and its paracancerous tissues suggesting that PPM1M was highly expressed in the paracancerous tissues of bladder cancer, while the expression levels decreased significantly in bladder cancer." (PMID 36961170, 2023).
colon adenocarcinoma (1 paper, 2023). "The expression of PPM1M was downregulated in glioblastoma multiforme (GBM) (P < .01), colon adenocarcinoma (COAD), brain lower-grade glioma (LGG), pancreatic adenocarcinoma (PAAD), and rectal adenocarcinoma (READ) (P < .05)." (PMID 36961170, 2023).
colon cancer (1 paper, 2023). "Using the human protein atlas (HPA) database, the results suggested that the expression of PPM1M was high in the normal bladder and colon tissues, whereas the expression levels were significantly decreased in the bladder and colon cancer tissues." (PMID 36961170, 2023).
dementia with (1 paper, 2025). "The PPM1M D440N variant was also identified in three additional subjects from other PD cohorts: once in 700 cases from the Mayo Clinic’s brain bank in a subject with dementia with Lewy bodies; once in 725 PD cases from a Polish cohort; and once in 139 Ukrainian PD cases." (PMID 40166354, 2025).
diffuse large B-cell lymphoma (1 paper, 2023). "Deep deletions were the most common type of mutations in PPM1M, which was highest in diffuse large B-cell lymphoma (4.2%), whereas KIRC, MESO, and esophageal adenocarcinoma were almost more than 2%." (PMID 36961170, 2023). "Among the types of genetic alterations, PPM1M had the highest frequency of profound deletions, occurring most frequently in diffuse large B-cell lymphoma and least frequently mutated in patients with LUAD." (PMID 36961170, 2023).
leukemia (1 paper, 2023). A malignant (clonal) hematologic disorder, involving hematopoietic stem cells and characterized by the presence of primitive or atypical myeloid or lymphoid cells in the bone marrow and the blood. "First, the differences in the expression of PPM1M in tumor tissues and paired normal tissues were compared, and PPM1M mRNA expression levels were found to be high in 8 normal tissues, including brain and CNS, breast, colorectal, esophageal, gastric, ovarian, prostate, lung, and leukemia." (PMID 36961170, 2023).
lymphoma (1 paper, 2023). A malignant (clonal) proliferation of B- lymphocytes or T- lymphocytes which involves the lymph nodes, bone marrow and/or extranodal sites. "Analysis of the Oncomine database showed that in most human normal tissues, including CNS, breast, colorectal, esophageal, gastric, ovarian, prostate, and lung tissues, PPM1M mRNA showed significantly high expression, whereas in malignant tissues, only lymphoma showed high expression." (PMID 36961170, 2023).
mesothelioma (1 paper, 2023). A usually malignant and aggressive neoplasm of the mesothelium which is often associated with exposure to asbestos. "There was a increasing trend in the expression of PPM1M in mesothelioma (MESO) and READ, but the difference was not statistically significant." (PMID 36961170, 2023).
Pancytopenia (1 paper, 2023). An abnormal reduction in numbers of all blood cell types (red blood cells, white blood cells, and platelets). "In this study, we investigated the expression of PPM1M in pancytopenia and its prognostic significance." (PMID 36961170, 2023).
testicular germ cell tumor (1 paper, 2023). A germ cell tumor arising from the testis. "In contrast, PPM1M was expressed at low levels in HNSC, STAD, and testicular germ cell tumors (TGCT)." (PMID 36961170, 2023).
cancer (1 paper, 2023). A tumor composed of atypical neoplastic, often pleomorphic cells that invade other tissues. "To investigate the relevance of PPM1M mutations in various human cancers, we extracted 33 tumor datasets from TCGA dataset using the cBioPortal database and examined PPM1M mutations." (PMID 36961170, 2023). "PPM1M is strongly linked to the regulation of the immune microenvironment in cancer and ligand-receptor interactions in immune cells." (PMID 36961170, 2023). "In this study, the correlation of PPM1M with TMB and MSI demonstrated that in malignant tumors, PPM1M is closely associated with the TMB." (PMID 36961170, 2023). "We continued to investigate the expression levels of PPM1M in a variety of tumors at different stages, and the results demonstrated remarkable differences in KIRC, KIRP, LUAD, and TGCT, with the expression levels of PPM1M in patients with cancer (stages I–II)." (PMID 36961170, 2023). "Additional clinical studies on tumor-based immunity are required to maximize the utility and effectiveness of PPM1M gene-based predictive biomarkers and to use them in precision medicine for patients with cancer." (PMID 36961170, 2023). "Based on the cancer genome atlas (TCGA) database, we performed pan-cancer expression analysis of PPM1M expression to determine the impact of PPM1M on the development and prognosis of cancer." (PMID 36961170, 2023). "To further study the effect of PPM1M on the prognosis of patients with cancer and OS, DSS, and PFI, we combined single-factor Cox regression analysis with Kaplan–Meier analysis." (PMID 36961170, 2023). "In this study, we investigated the role of PPM1M in pan-cancer." (PMID 36961170, 2023). "This suggests that PPM1M enhances T cell infiltration, which could explain its protective role in most types of cancer." (PMID 36961170, 2023). "Therefore, this is the first pan-cancer study conducted on the PPM1M gene." (PMID 36961170, 2023). "Thus, PPM1M may hold promise as a potential pan-cancer biomarker or as a novel immunological therapeutic target when used to predict immunotherapeutic responses or achieve a desired therapeutic outcome, respectively." (PMID 36961170, 2023). "However, the potential role of PPM1M in various types of tumors, the progression of human cancer, and evidence for human pan-cancer remain unclear." (PMID 36961170, 2023). "In pan-cancer, PPM1M affects patient prognosis and may be a potential immunological biomarker." (PMID 36961170, 2023). "CNV of PPM1M differed in pan-cancer with UCS, KIRP, and LGG positively correlated with PPM1M copy number, whereas BRCA, OV, COAD, LIHC, PCPG, and THCA were negatively correlated with PPM1M copy number." (PMID 36961170, 2023). "Furthermore, in-depth exploration of the PPM1M protein in stages I to II and III to IV of pan-cancer revealed that the expression levels in stages I to II were greater than those in stages III to IV in KIRP, LUAD, and TGCT." (PMID 36961170, 2023).
tumor (1 paper, 2023). "The expression of PPM1M is closely associated with patient prognosis, tumor immune checkpoint, tumor mutational burden, and microsatellite instability." (PMID 36961170, 2023). "The Sanger Box database was used to analyze the relationship between PPM1M and tumor immune checkpoint, tumor mutational burden, and microsatellite instability." (PMID 36961170, 2023). "PPM1M is closely associated with the infiltration of immune cells into the tumor microenvironment." (PMID 36961170, 2023). "Meanwhile, the data of the normal tissue from the GTEx database were integrated with the data of the tumor tissue from TCGA database, and joint analysis revealed that PPM1M was overexpressed in 24 tumors." (PMID 36961170, 2023). "Because of the small sample size of normal tissues in TCGA database, we combined the data of the normal tissue from the GTEx database with the data of the tumor tissue from TCGA database and performed a differential analysis of PPM1M expression in 27 tumors." (PMID 36961170, 2023). "The Tumor Immune Estimation Resource 2 database and CIBERSORT method were used to analyze the relationship between PPM1M and tumor-infiltrating immune cells." (PMID 36961170, 2023). "Second, the results of testing the TCGA dataset suggested that the expression levels of PPM1M were significantly different in different tumor types." (PMID 36961170, 2023). "In this study, PPM1M was found to be overexpressed in 24 tumor types." (PMID 36961170, 2023). "Additionally, we found that the expression of the PPM1M gene plays a different role in tumor prognosis in different types of tumors." (PMID 36961170, 2023). "Thus, the differences in the expression of PPM1M in different tumor types suggest that PPM1M has different regulatory mechanisms in different tumor types." (PMID 36961170, 2023). "Furthermore, PPM1M may be a potential therapeutic target in tumor immunology." (PMID 36961170, 2023).
PPM1M also shares sentences with these, for which no sentence is quoted: cholangiocarcinoma (1 paper); endometrial cancer (1); esophageal adenocarcinoma (1); glioblastoma (1); infection (1); influenza (1); lung adenocarcinoma (1); lung squamous cell carcinoma (1); mental illness (1); ovarian carcinoma (1); pancreatic adenocarcinoma (1); paraganglioma (1); pheochromocytoma (1); prostate adenocarcinoma (1); rectal adenocarcinoma (1); sarcoma (1); schizophrenia (1); thymoma (1); thyroid cancer (1); uveal melanoma (1).